UCHL1 (ubiquitin C-terminal hydrolase L1)
Diseases named in the same sentence as UCHL1 in open-access papers (continued):
Sharing a sentence is not in itself a finding about the gene and the disease.
neurodegenerative disease (60 papers, 2008 to 2025). A disorder of the central nervous system characterized by gradual and progressive loss of neural tissue and neurologic function. "After analyzing the KEGG pathways, the UCHL1 protein was associated with the neurodegenerative disease pathway, so the levels of the proteins involved in this pathway were examined by Western blot." (PMID 40869913, 2025). "The analysis added validity and served as a “positive control” to our results, as it is well known that UCHL1 is implicated in neurodegenerative diseases." (PMID 40078282, 2025). "In particular, UCHL1 can enhance the cyclin-dependent kinase activity implicated in the pathogenesis of neurodegenerative diseases." (PMID 38727276, 2024). "UCHL1 comprises approximately 1–5% of the total soluble protein in the brain and is implicated in the progression of neurodegenerative diseases." (PMID 33668938, 2021). "The lncRNA AS-Uchl1 is an antisense RNA that seems to increase the translation of UCHL1, a deubiquitinating enzyme whose reduction is associated with neurodegenerative diseases and mutations in the Uchl1 gene are found in familial Parkinson’s disease (PD)." (PMID 34203457, 2021). "The sudden cardiac death in both patients highlights the importance of cardiac follow-up and treatment in neurodegenerative disease associated with UCHL1 mutations." (PMID 32656641, 2020). "Although it is highly expressed in human brain tissues (GTEx database), UCHL1 is implicated in neurodegenerative diseases." (PMID 31608105, 2019). "It was originally discovered for its role in increasing translation of Uchl1 mRNA, a gene associated with neurodegenerative diseases." (PMID 29453387, 2018). "UCHL1 is involved in synaptic activities and a reduction in UCHL1 function has been linked to neurodegenerative diseases." (PMID 26881020, 2016). "Ubiquitin-C-terminal hydrolase L1 (UCH-L1) is a brain-specific deubiquitinating enzyme that has been linked to neurodegenerative diseases." (PMID 26539913, 2015). "This is mutated in rare cases of early-onset familial Parkinson's Disease (PD) and loss of UCHL1 activity has been reported in many neurodegenerative diseases." (PMID 25883552, 2015). "Thus, dysfunction of UCHL1 has been directly implicated in neurodegenerative diseases, such as AD." (PMID 26881020, 2016). "Changes in UCHL1 expression are observed in both neurodegenerative diseases and affective disorders." (PMID 41155506, 2025). "While UCHL1 is known to be predominantly expressed in the brain and plays a central role in neurodegenerative diseases, studies have also established its function in ovarian development and fertility." (PMID 40078282, 2025). "UCHL1 is a 25 kDa protein that exists in the brain and participates in the progression of neurodegenerative diseases." (PMID 37246623, 2023). "UCHL1 is a deubiquitinating enzyme that is involved in the pathogenesis of neurodegenerative diseases, including AD." (PMID 35054106, 2022). "The ubiquitin carboxy-terminal hydrolase L1 gene (Uchl1) has been shown to be closely related to brain function and neurodegenerative diseases." (PMID 29499939, 2018). "Several proteins were associated with neurodegenerative diseases, DPYSL2 and TPI1 were related to AD, UCHL1 was linked to PD, whereas ALDH was related to AD and PD." (PMID 27857231, 2016). "An antisense transcript to mouse ubiquitin carboxy-terminal hydrolase L1 (Uchl1), which is involved in neurodegenerative diseases, increases the translation of Uchl1." (PMID 27493656, 2016). "This is particularly relevant considering that UchL1 is target of oxidative stress inactivation and is down-regulated in post-mortem brains of neurodegenerative diseases." (PMID 25883552, 2015). "In our study, we present five proteins that are also regulated in neurodegenerative diseases: UCHL-1, transhtyretin, Apolipoprotein A1, DRP-2 and DRP-3." (PMID 21470419, 2011).
neurodegenerative disease (continued). "The four folds upregulation of ubiquitin C-terminal hydrolase L1 (UCHL1) and PPP2R2D, a subunit of protein phosphatase 2A, suggests altered signalling pathways and protein turnover in human brain, which are associated with neurodegenerative diseases." (PMID 40520681, 2025). "We hypothesized that UCHL1 was likely released from CSF into the peripheral circulation via impaired blood-brain barrier, which is involved in the course of neurodegenerative diseases." (PMID 31932518, 2020). "For example, increasing data indicated that an increase in Uchl1 expression could be advantageous in neurodegenerative diseases, the application of AS-Uchl1 as an RNA-target drug may be considered a novel therapeutic tool." (PMID 32899172, 2020). "Since UCHL1 protein has been shown to contribute to the progression of neurodegenerative diseases, AS Uchl1, as its upstream regulator, could be envisioned as a new therapeutic target." (PMID 29719633, 2018). "Similarly, lncRNA antisense-Uchl1 is involved in brain function and neurodegenerative diseases by increasing UCHL1 protein synthesis." (PMID 28522862, 2017). "Dysfunction in UCHL1 has been reported in many neurodegenerative diseases." (PMID 25883552, 2015). "Finally, since increasing evidences suggest Uchl1 over-expression could be beneficial in neurodegenerative diseases, the use of AS Uchl1 as RNA-based drug may represent a new therapeutic strategy." (PMID 25883552, 2015). "Furthermore, they suggest that increasing UCHL1 expression in vivo may be a safe and effective disease-modifying strategy to treat neurodegenerative diseases." (PMID 25883552, 2015). "Lnc AS Uchl1 (ubiquitin C-terminal hydrolase L1) intensifies translation of UCHL1, which plays an important role in the ubiquitin proteasome system (UPS) and in many other cellular processes such as differentiation, cell proliferation, as well as in brain function and in neurodegenerative diseases." (PMID 32489713, 2020). "Generation and characterization of the UCHL1-eGFP mouse, in which the CSMN are genetically labeled, has been pivotal for overcoming numerous important limitations by allowing in vivo visualization and cellular analysis of neurons that are vulnerable in neurodegenerative diseases." (PMID 24723858, 2014).
neurological disorders (23 papers, 2009 to 2026). "As of now, five missense mutations in UCHL1 has been associated with PD and other neurological disorders, i.e. E7A, S18Y, I93M, R178Q and A216D." (PMID 33028204, 2020). "Mutations and functional aberrations of UCHL1 are associated with several neurological disorders." (PMID 41036271, 2025). "Furthermore, we also performed comparative structural analysis of previously reported PD and other neurological disorders causing missense mutations of UCHL1 (between wild type and all five PD and other neurological disorders causing mutant versions)." (PMID 33028204, 2020). "In addition, previously reported 5 PD and other neurological disorders associated missense mutations (E7A, S18Y, I93M, R178Q and A216D) are also localized to the C-12 peptidase domain except A216D which resides at the C-terminal of human UCHL1." (PMID 33028204, 2020). "It has been reported that UCHL1 plays an important role in the occurrence and development of neurological diseases and other diseases." (PMID 35546675, 2022). "Another deubiquitination enzyme, ubiquitin C-terminal hydrolase L1 (UCHL1), is crucial in neurological diseases." (PMID 34122010, 2021). "Given the vital role of UCHL1 in both familial and sporadic PD and other neurological disorders, the present study offers an insight into the evolutionary history of UCHL1 through evolutionary rate analysis and phylogenetic investigation." (PMID 33028204, 2020). "Serum samples were measured for several proteins known to be elevated in various forms of neurological disease or injury: neurofilament-light (NfL), glial fibrillary acidic protein (GFAP), tau and ubiquitin c-terminal hydrolase L1(UCHL1) 5–7." (PMID 36114333, 2022). "For example, levels of the brain-derived glial fibrillary acidic protein (GFAP), S100B, tau and Ubiquitin C-Terminal Hydrolase L1 (UCHL-1) in biological fluids have been shown to correlate with presence and severity of many neurological disorders." (PMID 27903281, 2016). "Some downregulated proteins such as DPYSL2, TPI1, ALDH, and UCHL1 were found to play critical roles in the neurological disease and PSMA1, PSMA3, PSMC2, PSMD11, and UCHL1 in protein homeostasis." (PMID 27857231, 2016).
infection (18 papers, 2013 to 2026). The state of being infected such as from the introduction of a foreign agent such as serum, vaccine, antigenic substance or organism. "The infection pattern in the rhinal cortex was also confirmed by confocal microscopy, where most infected cells displayed neuron-like morphology and co-stained with neuronal marker UCHL-1." (PMID 40827915, 2025). "After poly(I:C) infection, there was a downregulation of Uchl1 expression, while the expression of Tlr3, Caspase3, Caspase12, NOD-like receptor thermal protein domain associated protein 3 (Nlrp3), Interleukin-1β (IL-1β), IL-6, and Tumor necrosis factor alpha (Tnfα) was significantly upregulated." (PMID 38300431, 2024). "The successful overexpression of UCHL1 in NSCs was confirmed at 48 hours after infection." (PMID 37507386, 2023). "Moreover, ubiquitin C-terminal hydrolase L1 (UCHL1) was highly expressed after more than 30 days post-infection during establishment of EBV-transformed LCLs, and may be associated with EBER regulation." (PMID 35158879, 2022). "Moreover, expression of UCHL1 was upregulated 2 days post-infection of HPV16 in primary keratinocytes when compared to mock-infected primary keratinocytes, whereas knock-down of the polycistronic viral mRNA transcript in hrHPV+ KCs by siRNA for HPV16 E2 resulted in a decreased UCHL1 expression." (PMID 23717208, 2013). "Regarding DUB expression, no apparent differences were found throughout infection in the levels of HAUSP, also called USP7, UCHL1, A20, USP10, STAMBP, and CYLD." (PMID 36851696, 2023).
peripheral neuropathy (9 papers, 2015 to 2025). A disorder affecting the peripheral nervous system. "UCHL1 immunohistochemistry in combination with cutaneous nerve and skin biopsy has proven invaluable for clinical diagnosis of peripheral neuropathy." (PMID 26222784, 2015). "However, based on previous literature, UCHL-1 may play a role in the diagnosis and prognosis of peripheral neuropathies." (PMID 39565457, 2025).
heart diseases (5 papers, 2014 to 2024). "To date, only a few studies have assessed the role of UCHL1 in heart diseases." (PMID 32606430, 2020). "Ubiquitin C-terminal hydrolase L1 (UCHL1), a member of the UPS, is related to fibrosis in several heart diseases." (PMID 32606430, 2020).
digestive tumors (1 paper, 2012). "We also identified that UCHL1 methylation as a biomarker for HCC and other digestive tumors previously." (PMID 22279545, 2012).
UCHL1 also shares sentences with these, for which no sentence is quoted: Parkinson's (17 papers); concussion (13); cardiac arrest (10); cervical carcinoma (6); cerebellar ataxia (5); depression (5); hemorrhagic stroke (5); pancreatic neuroendocrine tumor (5); Sepsis (5); Encephalopathy (4); esophageal cancer (4); head and neck squamous cell carcinoma (4); optic atrophy (4); adenocarcinoma (3); Anxiety (3); focal segmental glomerulosclerosis (3); frontotemporal dementia (3); IgA nephropathy (3); invasive carcinoma (3); kidney disease (3); neuropathy (3); parathyroid neoplasms (3); acute appendicitis (2); acute lymphoblastic leukemia (2); B-cell chronic lymphocytic leukemia (2); colon adenocarcinoma (2); diabetic kidney disease (2); epileptic seizure (2); follicular carcinomas (2); hemorrhage (2).
A further 128 diseases each share a sentence with UCHL1 in 2 papers or fewer.